MYC (MYC proto-oncogene, bHLH transcription factor)
Diseases named in the same sentence as MYC in open-access papers (continued):
Sharing a sentence is not in itself a finding about the gene and the disease.
cancer (continued). "In a broad sense, c-MYC GCN gain of primary cancer tends to correlated with poor survival in advanced CRC." (PMID 26426996, 2015). "Cyclin D1 (CCND1), c-MYC, and DNA-binding protein inhibitor ID-2 (ID2) genes encode proteins strictly involved in cell proliferation and cancer development." (PMID 26450900, 2015). "Cancer-related genes with significant up-regulation in all ATCs included MYC, mTOR, PRKCA and TGFB1." (PMID 26680454, 2015). "The majority of MYC studies focus on its function in cancer due to the critical role of MYC in human cancer." (PMID 26003165, 2015). "Taken together, these results emphasize the critical role of MYC-regulated lncRNAs in MYC function and MYC-mediated regulation of the MYCLos in wide range of cancer types." (PMID 26003165, 2015). "In all of the 11 samples, MYC up-regulation was observed, in agreement with the oncogene function of MYC in cancers." (PMID 25903198, 2015). "Together these results suggest that the BTC ligands can reduce the expression of MYC protein in HepG2 cancer cells at mRNA and protein levels." (PMID 26286633, 2015). "Amplification of 8q24.21, containing MYC locus, shows high frequency in cancer and this locus is close to 8q24.3, which contains the MAPK15 gene." (PMID 26035356, 2015). "More importantly, a recent report has also highlighted the involvement of PVT1 in regulating MYC, which has been firmly established to play a role in cancer." (PMID 26545364, 2015). "MYC is one of the most frequently activated oncogenes and its expression correlates with poor prognosis in several human cancers." (PMID 25884680, 2015). "At the copy number level, inter‐lesion differences involving cancer‐related genes were present, such as, for example, PTEN loss in only one of the lesions of patients PD4877, PD4878, and PD11773, and MYC amplification in one lesion from PD11776." (PMID 25850943, 2015). "c-MYC expression is essential for several metabolic alterations of cancer cells in order to fulfill their bioenergetic and biosynthetic demands." (PMID 26510913, 2015). "Only 10 (37%) amplified cases showed high-level gene amplification (≥10 MYC signals per cancer cell), including 4 cancers (#21, #40, #41, #43) with large MYC gene signal clusters." (PMID 25649416, 2015). "This agreement suggests that the MYC targets are found predominantly in chromatin regions active in mBL, IntL, GCB cells, the cancer cell line and lymphoblastoid cells (95% overlap between MYC targets and active promoters)." (PMID 26371046, 2015). "First, we sought to generate a cellular model for MYC conditional expression that recapitulates MYC deregulation in human cancer cells." (PMID 25669969, 2015). "In this review, we briefly discuss our current understanding of the basic features of lncRNAs and how they regulate the epigenetic landscape and then focus on the emerging dynamic relationships between MYC and several lncRNAs as they pertain to cancer." (PMID 27077133, 2015). "Together, these results suggest that MYC is dysregulated in USC and highlight the potential importance of MYC targeted therapy for this cancer type." (PMID 26170901, 2015). "Previous reports indicating that c-MYC was overexpressed in many types of cancers and contributed to drug resistance motivated us to investigate the role of c-MYC expression in 5-FU resistance in this study." (PMID 25689483, 2015). "For example, MYCLo-1 and MYCLo-3 are regulated by MYC not only in B cell but also in various types of cancer, suggesting their critical role in MYC-driven cancer." (PMID 26003165, 2015).
cancer (continued). "And MYC-repressed MYCLos as well as MYC-induced MYCLos are also regulated by MYC in various cancer types." (PMID 26003165, 2015). "We show that these MYC-repressed lncRNAs inhibit cell proliferation and that MYC induces cell proliferation by repressing these lncRNAs in cancer cells." (PMID 26003165, 2015). "The transcription factor c-MYC (hereafter termed MYC) and the related N-MYC and L-MYC oncogenes are involved in the development of up to 70% of all cancers." (PMID 26087190, 2015). "PVT1 is an exceptionally interesting lncRNA, both in its ability to physically interact with and regulate MYC and its pivotal roles in many cancers, making it an attractive therapeutic target to combat different cancers." (PMID 27077133, 2015). "Given the importance of MYC in the biology of cancer, many clinical researchers are trying to develop drugs that inhibit its activity." (PMID 25477524, 2015). "The proto-oncogene MYC is frequently amplified in human cancers andencodes the transcription factor c-Myc, which is associated with a variety of cellularprocesses such as cell growth and proliferation." (PMID 25621564, 2015). "We have previously reported that introduction of NS into TERT-immortalized fibroblast and cancer cells resulted in the significant increase of the expression of MYC, OCT4 and SOX2." (PMID 25569094, 2015). "The first 40Mb of canine chromosome 13 is syntenic to the last 48Mb of human chromosome 8q, which encodes genes including MYC and is one of the most recurrently amplified sites in human HNSCC and other cancer types." (PMID 26030765, 2015). "MYC-family transcription factors are key regulators of cell growth and survival, whose gene amplification is a common copy-number alteration in cancer, while over-expression or translocation of the MYC locus contributes to Myc activity deregulation." (PMID 25849938, 2015). "Gain of MYC was seen in two (16.7%) hyperplasias, 5 (9.1%) benign tumours and 14 (30.4%) malignant tumours." (PMID 25955013, 2015). "All proteins (Wnt4, MMP7, CD1 and c-MYC) tested were expressed in penile tissue (141 penile tissue cores from 101 unique tissue samples of which 18 were normal/cancer adjacent and 83 were malignant samples)." (PMID 25901368, 2015). "In the patient, there were losses of control pathway interactions with insulin and follicle stimulating hormone, and there were gains of interactions with MYC, a key transcription regulator in cancer." (PMID 26510912, 2015). "It cannot be excluded, however, that more cases with MYC amplification would have been identified if more than 9 cancer spots were analyzed." (PMID 25649416, 2015). "We tested combinations of the EGFR/ERBB2 inhibitor neratinib with the cell cycle inhibitors (BI-2536, GSK-1070916 and paclitaxel or docetaxel) in the MYC-amplified cancer cell line NCI-H82." (PMID 26018524, 2015). "Next, we showed that Loregic can make interpretable gate assignments for a cancer-related TF, MYC, which has been found to universally amplify target gene expressions in lymphocytes." (PMID 25884877, 2015). "In Mitelman's database of cytogenetic alterations in cancer, 62% of DH/TH cases had MYC/BCL2 translocations." (PMID 26416427, 2015). "YBX1 has already been reported as ITAF-like protein for c-MYC and is considered as an oncogene and a marker of aggressiveness for some cancer types." (PMID 26498684, 2015). "Obviously, impairment of this control loop by deletion of PTEN can be expected to provide a growth advantage to cancer cells beyond MYC amplification alone." (PMID 26672755, 2015). "Taken all together, the data are consistent with the notion that simultaneous inhibition of CDK9's kinase activity and MYC's expression or function leads to synergistic induction of growth arrest and apoptosis of cancer cells." (PMID 26083714, 2015).
cancer (continued). "Consistent with this idea, we show in the present study that simultaneous inhibition of CDK9's kinase activity and MYC's expression or function synergistically induced growth arrest and apoptosis of cancer cells." (PMID 26083714, 2015). "It is known that MYC is a downstream effector of ERBB2 signaling, that MYC-amplification results in Aurora kinase- dependent growth, and that co-amplification of ERBB2 and MYC is a frequent event in cancer." (PMID 26018524, 2015). "As MYC is the most frequently amplified oncogene in human cancers and plays a crucial role in transformation, therapies that exploit the spliceosome would be very attractive." (PMID 26490253, 2015). "The c-MYC proto-oncogene is a frequently activated oncogene and is estimated to be involved in 20% of all human cancers, affecting many cancer deaths." (PMID 25866480, 2015). "Among the genes harbored in 8q, studies have identified amplification of MYC on 8q24 as playing an important role in the development of different human cancers." (PMID 26307680, 2015). "The MYC proto-oncogene is deregulated in over half of human cancers including hematopoietic cancers, sarcomas, and carcinomas." (PMID 25669969, 2015). "Proto-oncogene c-MYC is a critical regulator of cellular metabolism and is frequently overexpressed in several types of cancer by different molecular mechanisms." (PMID 26046375, 2015). "We have previously reported that the AR promotes glycolysis and anabolic metabolism; many of these metabolic pathways are also MYC-regulated in other cancers." (PMID 25869206, 2015). "Identification of such “cancer driver genes” has facilitated the development of targeted treatment options in the recent years, yet there are still pharmacological limitations that hinder direct targeting of some major cancer drivers including MYC." (PMID 25669969, 2015). "Although MYC is the most frequently amplified oncogene in human cancers and plays a crucial role in transformation, therapeutic strategies that target MYC-driven tumors are very limited at present." (PMID 26490253, 2015). "In line with this notion, we found at least a strong trend towards an inferior prognosis for HER2 and/or MYC-amplified cancers with co-deletion of PTEN as compared to tumors harboring only one of these alterations." (PMID 26672755, 2015). "We then examined the expression of c-MYC in SIRT3-overexpressed cancer cell lines and control cells." (PMID 26317998, 2015). "The densitometric analysis of the blots revealed that the decrease of MYC expression in cancer cells is in the range of 85 ± 3% and 52 ± 2% at 5.0 μM concentration of BTC f and BTC c, respectively." (PMID 26286633, 2015). "The c-MYC oncogene is overexpressed in a broad spectrum of human malignancies and emerged as a potential therapeutic target for cancer treatment." (PMID 26286633, 2015). "For example, SFRP4, WNT11, FZD2, MYC were highly expressed in cancer tissues which represent the Wnt pathway was activiated and BCL2A1, ICM1, TNFSF14 in NF-κB pathway were highly expressed as well." (PMID 25928635, 2015). "MYC transcriptionally regulates ~500 core targets with as many as 2000 additional cancer and/or cell type-specific targets, making pharmacologic targeting downstream of MYC proteins challenging." (PMID 26029667, 2015). "CFA 13 harbors several key cancer genes, most notably the c-MYC and c-KIT proto-oncogenes; however, CFA 13 gain manifests primarily as a whole chromosome aneuploidy, in contrast to the recurrent focal deletion of CFA 11q16." (PMID 25957863, 2015). "MYC is primarily overexpressed and/or amplified in numerous types of cancer through various mechanisms such as retroviral transduction and MYC translocation." (PMID 26003165, 2015).
cancer (continued). "The published data indicate that BRD4 and its recruitment of P-TEFb to the MYC promoter region play a particularly important role in MYC expression in human cancer cells." (PMID 26083714, 2015). "The well-established oncogene MYC maps to this locus and likely contributes to the pathophysiology of cancers in which it is amplified." (PMID 25890171, 2015). "Here the lncRNA and MYC act in conjunction towards cancer progression, where the lncRNA regulates the phosphorylation of the MYC protein and protects it from destabilization and degradation." (PMID 26087192, 2015). "We identified overlapping MYC consensus binding sites in a minimum of three cancer cell lines lying at the transcription start sites (TSS) of every gene in the pathway." (PMID 25869206, 2015). "In light of HuR’s broad influence over diverse critical pro-survival pathways, HuR inhibition provides a unique therapeutic opportunity observed with just a handful of master regulators of cancer biology (e.g. MYC)." (PMID 26314962, 2015). "According to this study, PVT1 controls levels of MYC through regulation of the protein stability and they both cooperate to promote cell proliferation in cancer." (PMID 25883951, 2015). "Cox proportional hazard regressions indicate that NAMS is a robust prognostic gene signature, independent of other clinical and pathological factors including patient age, gender, smoking, gene alteration, MYC level, and cancer stage." (PMID 26596768, 2015). "Last, CIBLIN regulators are co-expressed with MYC in cancer transcriptomes, and many have already been identified as drivers and/or markers of aggressive cancer types." (PMID 26173873, 2015). "In the present study, we assessed the effect of glucose deprivation (GD) on c-MYC protein in several cancer cell lines." (PMID 27551483, 2015). "Obvious candidates for investigation are TERT at 5p15.33 and MYC at 8q24.21, in which SCNA were identified in multiple cancer types matching SNP associations in those genomic regions." (PMID 26575185, 2015). "Transgenic mouse models employing strategies that enable the conditional expression of oncogenes have been used to illustrate that cancers initiated by an oncogene, such as MYC, RAS, BCR-ABL, MET, and BRAF, are reversible upon suppression of the oncogene." (PMID 25089198, 2014). "In support of this notion, both AKT1 and c-MYC synergistically promote metabolic reprograming and aerobic glycolysis in cancer cells." (PMID 24628780, 2014). "To summarize, MYC regulates glutamine uptake and metabolism in cancer cells in at least three distinct ways." (PMID 25085992, 2014). "While the function of MYC has been well studied in the context of cancer cell growth and proliferation, the role of MYC in cellular differentiation has been less clear." (PMID 25437437, 2014). "Collectively, these data indicate that PRKDC modulates c-MYC mRNA and protein expression in these cancer cell lines; the effect on MYC protein abundance is at least in part through reduction of MYC mRNA." (PMID 25495526, 2014). "In fact, the down-regulation of c-MYC triggers the inhibition of cancer cell proliferation, invasion and migration." (PMID 24946763, 2014). "HIFs, as well as MYC, are pivotal factors for tumorigenesis in many types of human cancers and are able to activate LDHA." (PMID 24884974, 2014). "MYC is frequently altered in human cancer and has been reported to regulate many glucose metabolism genes, such as glucose transporter GLUT1 and hexokinase 2 (HK2)." (PMID 24884974, 2014). "MYC is involved in cell proliferation and its persistent expression is common to many cancers, while TBP is related to RNA polymerase II, an essential element of DNA transcription initiation." (PMID 24932011, 2014). "The challenge is now to identify the cancer-relevant lncRNA targets of MYC and determine their functions." (PMID 25587025, 2014).
cancer (continued). "At the molecular level, we found that inhibition of PRKDC downregulated MYC mRNA and protein expression in multiple cancer cell lines." (PMID 25495526, 2014). "Brd4, an epigenetic regulator of MYC, has been identified as a promising drug target for MYC-driven cancer." (PMID 25495526, 2014). "Although MYC has been well studied in the context of TERT regulation in cancer cells, the stability of TERT suppression by MYC inhibition is not well understood." (PMID 24550717, 2014). "MYC is commonly amplified in many cancers including HCC and higher expression level of MYC is associated with more advanced status of HCC." (PMID 24633177, 2014). "A specific MYC module active in ESCs was recently shown to be particularly important for cancer development." (PMID 25115192, 2014). "Although transcription factors are challenging to target pharmacologically using small molecules, recent studies have reported encouraging results with inhibition of MYC in preclinical models of fibrosis and cancer." (PMID 25080971, 2014). "The discovery of chromosomal rearrangements of the human MYC gene in Burkitt's lymphoma was the first link of the cellular homolog of a retroviral oncogene to human cancer." (PMID 25326649, 2014). "MYC is deregulated or overexpressed in most cancer cells and MYC inhibition is a therapy for cancer." (PMID 24637666, 2014). "In our quest to reveal novel synthetic lethal genes in the context of MYC-deregulated cancers, we conducted a pooled shRNA screen using isogenic cell lines." (PMID 25495526, 2014). "The traditional view of MYC-driven tumorigenesis is that the MYC protein behaves as a classical transcription factor, which regulates the expression of a specific set of downstream genes that contribute to cancer progression." (PMID 25587025, 2014). "It is well known that deregulated expression or malfunction of the transcription factor MYC is one of the most common abnormalities in human cancers." (PMID 24968068, 2014). "Collectively, these findings suggest that MYC can selectively be targeted in cancer by disablingthe HUWE1 ubiquitin ligase that normally controls MIZ1 protein levels (Fig1)." (PMID 25368331, 2014). "The activation of MYC facilitates the Warburg effect (aerobic glycolysis) and induces glycolysis and glutaminolysis, two typical metabolism alterations present in cancer cells." (PMID 24889866, 2014). "Together, our results suggest that the MYC oncogenic effect is dependent on PRKDC expression in multiple human cancers with high MYC expression levels." (PMID 25495526, 2014). "In particular, we find significant evidence that the AP1/MYC TF pair has an important role in regulating gene expression in cancers." (PMID 24612742, 2014). "Cancer cells with an aberrantly high expression of MYC often have deregulated cellular metabolism, particularly increased glycolysis and glutaminolysis." (PMID 25339305, 2014). "This appears to be similar to other pleiotropically acting transcription factors: for instance, MYC is a cancer-driving oncoprotein and it is known to transcriptionally activate both pro-survival and pro-apoptotic genes." (PMID 24586203, 2014). "miRNA let-7 is a master regulator of differentiation 42, frequently reduced or lost in a range of cancers 43, and is negatively regulated by c-MYC." (PMID 24403055, 2014).